TRPV1 (transient receptor potential cation channel subfamily V member 1)
Diseases named in the same sentence as TRPV1 in open-access papers (continued):
Sharing a sentence is not in itself a finding about the gene and the disease.
diabetes (continued). "It is also important to note that the culture conditions used by us were in complete absence of glial cells (removed by ARA-C treatment) and any diabetes-inducing drugs, such as STZ, which could interfere with normal expression of TRPV1 channels." (PMID 29474476, 2018).
asthma (71 papers, 2007 to 2025). "In patients with asthma and in those with chronic obstructive pulmonary disease (both conditions associated with chronic cough), TRPV1 expression and cough responses to TRPV1 agonists are increased." (PMID 37985513, 2023). "It has been found that a mutation of the TRPV1 gene is closely related to the development of asthma in children." (PMID 34356881, 2021). "LPAr 1, 2, 4, 5, 6 and TRPV1 mRNA are expressed in the petrosal ganglia of naïve animals; asthma causes upregulation of carotid body and petrosal LPAr mRNA (1>4>2>5>6), but the level of PKCε and TRPV1 mRNA expression is unchanged." (PMID 34465362, 2021). "This loss-of-function TRPV1 variant also correlated with a decrease in cough and wheezing severity in asthma patients." (PMID 34356881, 2021). "Bronchospasm and asthma-like symptoms developed in response to the action of cold air and high humidity are associated with the participation of TRPV1, TRPV4, and TRPV2 channels in osmoreception." (PMID 34356881, 2021). "At these sites, TRPV1 serves as a potential drug target for treating various diseases such as cystitis, asthma and hearing loss." (PMID 28658281, 2017). "In another study, TRPV1 gene expression and Th1/Th2 cytokines were found to be increased compared to controls and associated with childhood onset asthma." (PMID 27255083, 2016). "At these sites, activation of TRPV1 has been implicated in the pathophysiology of diseases such as cystitis, asthma and hearing loss." (PMID 24861977, 2014). "A recent study demonstrated a functional association between a specific polymorphism, TRPV1-I585V, with childhood asthma." (PMID 24861977, 2014). "It has been reported that the loss of function of TRPV1 genetic variant is associated with lower risk in active childhood asthma, with the reason of intracellular Ca2+ dysregulation induced by TRPV1 channel." (PMID 24010863, 2013). "Further, 12/15-LOX metabolites such as 13-S-HODE cause mitochondrial dysfunction in airway epithelia in asthma pathogenesis by activating TRPV1." (PMID 23840225, 2013). "In subjects with asthma, two TRPV1 SNPs were associated with usual cough, but the associations did not remain significant after correction for multiple testing." (PMID 22443337, 2012). "In subjects with asthma, the association between occupational exposure and usual cough and chronic cough appeared to be modified by TRPV1 rs224498." (PMID 22443337, 2012). "TRPV1 is associated with the major features of asthma, such as inflammation, AHR, and remodeling." (PMID 40276777, 2025). "Similarly, TRPV1, expressed in airway epithelial cells and immune cells, has been linked to asthma severity." (PMID 39664985, 2024). "Moreover, viral infections occurring during early childhood are related to asthma onset, and genetic variants in ADRβ2 and TRPV1 can influence disease severity and patient response to treatment." (PMID 39408565, 2024). "This suggests that variations in TRPV1 function may play a role in modulating the risk and severity of asthma in affected individuals." (PMID 37841931, 2023). "This response was also observed through the positive modulation of TRPV1 channels, taking into account that the neurogenic inflammation caused by the release of these neuropeptides contributed to the worsening of asthma." (PMID 37841931, 2023). "This suggests that variations in TRPV1 function may play a role in modulating asthma risk and severity in affected individuals." (PMID 37841931, 2023). "Furthermore, the corresponding TRPV-1 I585 mutation is associated with a higher risk of wheeze and cough in children with asthma." (PMID 34805220, 2021). "TRPV1 is significantly higher expressed in bronchial epithelia of asthma patients than in healthy volunteers and a loss of function single nucleotide polymorphism (SNP) changing the amino acid isoleucine to valine (I585V) lowers the risk of active childhood asthma." (PMID 30717260, 2019).
asthma (continued). "In urban particle matter and formaldehyde (FA) induced murine asthma model upregulated expression of TRPV1 was associated with enhanced release of pro-inflammatory neuropeptides such as substance P and Calcitonin Gene–Related Peptide (CGRP), which contributed to neurogenic inflammation." (PMID 31681615, 2019). "In addition to these inflammatory mediators, acidic pH associated with inflammation can contribute further to TRPV1-mediated airway hypersensitivity during asthma." (PMID 27322240, 2016). "Since its discovery, evidence has accumulated that TRPV1 has the potential to play a key role in a variety of pathologies, especially those associated with imbalances of the immune and inflammatory response, such as asthma and rheumatoid arthritis." (PMID 25242870, 2014). "It has recently been shown that the TRPV1 Ile585Val single nucleotide polymorphism (SNP) results in a loss-of-channel function, and that this SNP is associated with a lower risk of cough and wheezing among children with asthma." (PMID 22443337, 2012). "The role of the other subfamilies of TPRV in VILI still needs to be elucidated and might be promising because they are reportedly involved in ovalbumin-induced asthma models (TRPV1, TRPV2, TRPV5), and lung epithelial injury caused by cigarette smoke, LPS, seawater inhalation and wood smoke (TRPV3)." (PMID 39664395, 2024). "Channel proteins are expressed in sensory neurons, epithelial cells, and immune cells.TRPV1 mRNA expression is significantly upregulated in the nerves of a mouse model of asthma." (PMID 39958344, 2025). "While some studies confirm that certain CHM metabolites can alleviate asthma symptoms by activating TRPV1/TRPA1, drug development has primarily focused on TRPV1/TRPA1 inhibitors." (PMID 40678720, 2025). "Increasing evidence suggests that Chinese herbal medicines (CHM) exert beneficial effects in asthma treatment by modulating TRPV1/TRPA1." (PMID 40678720, 2025). "It is well-known that certain exogenous or endogenous stimuli can trigger asthma responses by activating TRPV1/TRPA1." (PMID 40678720, 2025). "During the course of asthma, TRPV1/TRPA1-mediated calcium influx induces the release of neuropeptides, including SP, NKA, NKB, and CGRP." (PMID 40678720, 2025). "In this paper, we provide an overview of the ameliorative or therapeutic effects of CHM or their extracts on asthma, offering a reference for the development of new drugs modulating TRPV1/TRPA1 for asthma treatment." (PMID 40678720, 2025). "TRPV1 mRNA expression is significantly increased in the neurons of a mouse model of asthma, rendering TRPV1+ nerve fibres highly sensitive." (PMID 39958344, 2025). "Recently, the role of TRPV1/TRPA1 activation in exacerbating asthma symptoms and its specific mechanisms have become increasingly clear, sparking interest among asthma drug development researchers in targeting TRPV1/TRPA1 antagonists." (PMID 40678720, 2025). "Increasing evidence demonstrate the essential function of transient receptor potential vanilloid family (TRPV1, 2, and 4) in the pathogenesis of asthma." (PMID 40276777, 2025). "Given their pivotal roles in asthma pathophysiology, TRPV1 and TRPA1 have emerged as promising therapeutic targets for developing novel disease-modifying agents." (PMID 40678720, 2025). "Studies have shown that polymorphisms in the TRPV1 and TRPA1 are closely associated with the pathophysiological processes of asthma." (PMID 40678720, 2025). "Studies have shown that patients with severe asthma exhibit elevated TRPV1 expression in the airway epithelium, and asthmatic children present higher levels of TRPV1 gene expression compared to healthy controls." (PMID 39664985, 2024). "Genetic ablation or pharmacological disruption of TRPV1 attenuates airway injury and asthma in murine models of allergic airway inflammation while TRPV1 denervation decreases dendritic cell numbers in response to antigenic challenge." (PMID 38807193, 2024).
asthma (continued). "Relevant studies indicate that high humidity levels exceeding 90% can induce oxidative stress, activate the TRPV1 pathway, and promote type I hypersensitivity, thereby contribute to the development and progression of asthma." (PMID 39713043, 2024). "Several publications have established a connection between TRPV1 activation in the airways and asthma or NAR." (PMID 36676189, 2023). "TRPV1 is also known to be involved in cough, asthma, pain, inflammation, pruritus, auditory sensation, taste, apoptosis, oxidative stress, and other physiological and pathological processes in the body." (PMID 37025492, 2023). "Human studies reveal that patients with severe asthma have been reported to exhibit an increase in TRPV1 expression in the airway epithelium." (PMID 37841931, 2023). "Murine asthma models show upregulation in TRPV1 expression, which enhances the release of SP and CGRP and contributes to neurogenic inflammation, while CPZ treatment effectively reduces proinflammatory neuropeptides." (PMID 36350149, 2022). "In this study, the mechanisms of ACH, BCH, and their combination (SGMHD) on asthma inflammation and regulation of TRPV1 and TAS2R14 were discussed from the level of animal experiments." (PMID 36045655, 2022). "In airway diseases such as asthma and chronic obstructive pulmonary disease, the expression of TRPV1 in bronchial fibroblasts is upregulated in the presence of potential inflammatory stimuli." (PMID 35911651, 2022). "Irritant gases such as vanillic acid analogies can trigger subsequent inflammatory pathways by activating TRPV1, leading to asthma." (PMID 36045655, 2022). "In CRSwNP patients, one study found decreased TRPV1 and TRPA1 mRNA levels in nasal mucosa, whereas TRPV1 was upregulated in case of comorbid asthma or allergy." (PMID 33738577, 2021). "TRPA1 is thought to initiate the asthma episodes via activation by cigarette smoke, chlorine, aldehydes and scents, while TRPV1 regulates inflammation and cell proliferation." (PMID 33803491, 2021). "Particular attention is paid to TRPV1-mediated induction of cough as the result of inhalation of irritating environmental reagents and in asthma." (PMID 34356881, 2021). "In this section, we outline the pathophysiological role of TRPV1 in chronic airway diseases such as asthma and COPD." (PMID 31496955, 2019). "The authors suggest a role of TRPV1 channels especially in patients with severe, uncontrolled asthma." (PMID 30087301, 2018). "Behavioral indices of airway resistance (Ti:Te) were reduced ~60% by combined blockade suggesting that the bulk of neurogenic bronchoconstriction in the ovalbumin rat model of asthma is dependent on the LPAr + TRPV1 pathway." (PMID 30279412, 2018). "Further corroborating this concept, the ablation of the nociceptor by using the Nav1.8-Cre/DTA mice strain or using interference RNA for TRPV1 reduce these same parameters in allergic rhinitis and asthma models, suggesting an endogenous role for TRPV1." (PMID 27367653, 2016). "The aim of these experiments was to demonstrate the importance of CD4+ T cells and the role of TRPV1 in an asthma model using a clinically ready TRPV1 inhibitor (XEN-D0501) and genetically modified (GM) animals." (PMID 27255083, 2016). "Expression of TRPV1 is markedly up-regulated in the bronchial epithelia and nasal mucosa of patients with refractory asthma." (PMID 26700618, 2016). "In order to confirm a role for TRPV1 in the asthma phenotype we employed an alternative model system/species configured in the Brown Norway rat and in this case utilised a clinically-ready pharmacological inhibitor, XEN-D0501." (PMID 27255083, 2016). "Increased TRPV1 expression in bronchial epithelium correlates with the severity of asthma, and TRPV1 agonist stimulation in bronchial epithelium induces IL-8 release in a dose-dependent manner." (PMID 26180629, 2015).
asthma (continued). "The role of TRPV1 in AHR has recently been demonstrated by the finding that oral administration of TRPV1-specific antagonists significantly attenuated AHR in the asthma model of OVA-sensitized guinea pigs." (PMID 25197168, 2014). "The polymorphism rendered these channels less responsive to activation by heat and capsaicin, indicating that TRPV1 plays an important role in the pathophysiology of asthma." (PMID 24861977, 2014). "We further demonstrated that linoleic acid metabolite, 13-S-HODE, can cause mitochondrial dysfunction in airway epithelia to drive severe asthma by activating transient receptor potential vanilloid type 1 (TRPV1)." (PMID 23840225, 2013). "Compared with the control group, the asthma group showed an increased expression of TRPV1 and [Ca2+]i in rat ASMC." (PMID 24010863, 2013). "TRPV1 is also shown to be involved in citric acid-induced cough, gastroeosphageal reflux-induced asthma as well as airway disorders induced following inhalation of acid fog or pollutants." (PMID 19305794, 2008). "Whereas MUC5AC and mucin 5B secretion are reduced in an asthma mouse model with TRPV1 knockout." (PMID 39958344, 2025). "Moreover, knocking out TRPV1 in house dust mite (HDM) or OVA-sensitized asthma mouse models led to an enhanced Th2 response." (PMID 40678720, 2025). "Therefore, this study systematically analyzed 134 articles covering the pathogenesis of asthma, current treatment strategies, the role of TRPV1/TRPA1 in asthma, and the modulation of TRPV1/TRPA1 by Chinese herbal medicines in asthma." (PMID 40678720, 2025). "Here, we summarize the pathological roles of TRPV1/TRPA1 in asthma." (PMID 40678720, 2025). "Additionally, certain air pollutants, such as dust and nitrogen compounds, can activate TRPA1 and TRPV1, promoting and worsening existing asthma." (PMID 38365763, 2024). "Since TRPV1 expression seems to be related to asthma severity, its suppression could be helpful in decreasing chronic airway epithelial injury and asthma features, as observed in animal models." (PMID 39408565, 2024). "The overexpression of functional TRPV1 channels in the airway epithelium of patients with refractory asthma may provide a new therapeutic target for such asthma." (PMID 36096782, 2022). "In severe asthma, TRPV1 expression is increased and TRPV1 responses are potentiated." (PMID 34557110, 2021). "Therefore, the development of bronchospasm and asthma-like symptoms in response to the action of hyper- and hypoosmolar exogenous stimuli is mediated by the vanilloid receptors, such as TRPV1, TRPV4, and TRPV2." (PMID 34356881, 2021). "Furthermore, upregulated TRPV1 expression and function in lung afferents is characteristic of such pathologic conditions as chronic cough, asthma, and pulmonary inflammation of various etiologies." (PMID 33613196, 2020). "Some studies suggest that TRPV1 activation leads to the release of pro-inflammatory cytokines in asthma, and TRPV1 antagonists could be used in the treatment of this disease." (PMID 32316328, 2020). "TRPV1 expression is also upregulated in the airway epithelium from patients with obstructive airway diseases characterized by chronic inflammation of the respiratory tract, such as asthma and in animal models of asthma." (PMID 33613196, 2020). "Similar phenomenon of TNF-α induced potentiation of Ca2+ current evoked by TRPV1 has been reported in rat pulmonary sensory neurons in asthma, in cultured trigeminal ganglions isolated from neonatal rats, in human synoviocytes and in sensitization of the spinal cord in the pain model." (PMID 31632242, 2019). "A recent study on the efficacy of anticholinergic agents in asthma demonstrated that tiotropium inhibits TRPV1-mediated effects of neural stimuli through a mechanism unrelated to its anticholinergic action, improves symptoms and attenuates capsaicin-induced cough in challenge studies." (PMID 29422039, 2018).
asthma (continued). "It has been suggested that SP and CGRP, released by an activated TRPV1 ion channel, contribute to inflammation in asthma by neurogenic inflammation, including the triggering of specific receptors, and the production of additional inflammatory mediators like cytokines, oxygen radicals and histamine." (PMID 28931832, 2017). "In other words, TRPV1 acts a key part in this combined exposure contributed asthma." (PMID 28931832, 2017). "Furthermore, results suggested that co-exposure exacerbated the activation of TRPV1 signal pathways, with an enhancement in substance P and calcitonin gene-related peptide production, which contributed to inflammation in asthma by neurogenic inflammation." (PMID 28931832, 2017). "Capsazepine (Cpz) was used to verify the specific mechanism of TRPV1 in aggravated asthma." (PMID 28931832, 2017). "More recently, we have also shown the involvement of neuro-immune interactions, with a role for airway sensory nerves expressing the chemo-receptors transient receptor potential (TRP)A1 and TRPV1, lymphocytes and mast cells in our model of chemical-induced immune-mediated paucigranulocytic asthma." (PMID 28704401, 2017). "Furthermore, inflammatory stimuli have been reported to increase the expression of TRPV1 and other studies have suggested an increase in TRPV1 expression in asthmatic patients and also in animal models of asthma." (PMID 27255083, 2016). "Increased production of NGF during asthma can potentiate inflammation through TRPV1 sensitization." (PMID 27322240, 2016). "Furthermore, in an in vivo asthma model, TRPV1 antagonist, N-(4-tertiarybutylphenyl)-4-(3-chloropyridin-2-yl)tetrahydropyrazine-1(2H)-carbox-amide (BCTC), attenuated the coughing induced by allergens." (PMID 24861977, 2014). "The present study showed significant associations between TRPV1 SNPs and cough symptoms among subjects without asthma from two independent European studies." (PMID 22443337, 2012). "TRPV1 SNPs were associated with cough among subjects without asthma from two independent studies in eight European countries." (PMID 22443337, 2012). "In subjects without asthma, 10 TRPV1 SNPs were associated with nocturnal cough (4.3 × 105 ≤ p ≤ 0.044), 6 TRPV1 SNPs were associated with usual cough (2.0 × 10-5 ≤ p ≤ 0.046), and 4 TRPV1 SNPs were associated with chronic cough (0.005 ≤ p ≤ 0.045)." (PMID 22443337, 2012). "In subjects without asthma, three TRPV1 SNPs appeared to modify the association between current smoking and cough symptoms (9.0 × 10-4 ≤ p interaction ≤ 0.030)." (PMID 22443337, 2012). "TRPV1 SNPs were associated with nocturnal, usual, and chronic cough in subjects without asthma from two independent studies in eight European countries." (PMID 22443337, 2012). "In the present analysis, TRPV1 I585V was also associated with a lower risk of nocturnal cough in EGEA adults with asthma (OR 0.62 [0.40-0.96], p = 0.03), but the association was not statistically significant in the pooled analysis." (PMID 22443337, 2012). "Chronic airway inflammation such as in asthma or COPD may increase the sensitivity of TRPV-1 to its agonists and trigger the cough reflex." (PMID 18154688, 2007). "Consequently, antagonism of TRPV1/TRPA1 channels exerts beneficial effects on asthma symptoms." (PMID 40678720, 2025). "Similarly, TRPV1 expressed in airway C-fiber afferent neurons can be activated by endogenous activators or inhaled irritants, a phenomenon observed in patients presenting with asthma." (PMID 37240671, 2023). "Thus, TRPV1 expression may be an important mechanism for asthma exacerbation upon exposure to ozone and other environmental pollutants." (PMID 31608051, 2019). "In addition, a report on transient receptor potential vanilloid 1 (TRPV1) polymorphisms associated with cough in subjects without asthma has been published while recent studies have further shown TRPA1 as a promiscuous receptor for a wide range of stimuli." (PMID 27517941, 2016).